LIN28B (lin-28 RNA binding posttranscriptional regulator B)
Diseases named in the same sentence as LIN28B in open-access papers (continued):
Sharing a sentence is not in itself a finding about the gene and the disease.
tumor (continued). "Compared with the control group, Lin28B knockdown reduce the average volume of xenografts in nude mice, while overexpression of PCAT5 can save the tumor growth inhibition of Lin28B knockdown." (PMID 38565547, 2024). "Disruption of the LIN28B/let-7 miRNA interaction restores the tumor suppressor let-7 miRNA levels, providing a potential new therapeutic target in oncology." (PMID 38732012, 2024). "Studies have found that LIN28B plays a basic role in maintaining the glycolytic metabolism of tumor stem cells." (PMID 38565547, 2024). "Results showed that the mRNA levels of BNIP3, CYCS, RRAGD, CD44, EIF4E, MAP4K1, and LIN28B were higher in tumor samples, whereas the mRNA levels of PPARGC1A and FLT3 were higher in normal samples." (PMID 38468074, 2024). "Our mechanistic analysis showed that circ_0067557 can play a sponge role in binding to its targets Lin28A and Lin28B, and play an important role in tumor progression and chemoresistance of CRC." (PMID 38216964, 2024). "In OS13 cells, knocking down LIN28B can reduce tumor occurrence, reduce chemotherapy resistance, and reverse oxidative phosphorylation." (PMID 38565547, 2024). "In various NB initiation and progression models, elevated levels of LIN28B, MYCN and ODC1 have been associated with increased tumor initiation and progression due to increased proto‐oncogene activity and ensuing progenitor‐like cells." (PMID 38686627, 2024). "Similar to the DEN-induced HCC progenitors, these lesions expressed IGF2BP3 and were LIN28B but not LIN28A positive, suggesting a greater importance for LIN28B in tumor initiation." (PMID 38875287, 2024). "To examine the role of the LIN28B pathway on tumor growth in vivo, we injected the LIN28B knockdown and corresponding control Group 3 MB cells into the cerebella of immunocompromised (NSG) mouse pups (p3‐p5)." (PMID 37341142, 2023). "Immunofluorescence staining showed that silencing Lin28b in tumor reduced stromal Lin28b expression in orthotopic models." (PMID 37898598, 2023). "We then utilized RNA-sequencing (RNA-seq) of 15376T, Lin28b-KO 15376T, and 14837T to further understand the mechanisms by which tumor cells upregulate stroma Lin28b expression." (PMID 37898598, 2023). "LIN28B is an inhibitor of maturation of the let‐7 miRNAs, which have been well characterized as a family of tumor suppressor miRNAs." (PMID 37341142, 2023). "Immunofluorescence staining showed that knocking-‍out Wnt5a in tumor reduced stromal Lin28b expression in orthotopic models." (PMID 37898598, 2023). "We then found that CM from CAFs expressing Lin28b was able to rescue tumor growth under glucose-limiting conditions." (PMID 37898598, 2023). "Using an orthotopic mouse model of PDAC, we find that depletion of Lin28b in CAFs reduced tumor weight, highlighting the importance of Lin28b in PDAC stroma." (PMID 37898598, 2023). "Work in mouse models suggests that activation of LIN28B alone is sufficient to initiate tumour formation." (PMID 37269361, 2023). "Fzd4-positive CAFs was able to rescue tumor growth both in vitro and in vivo, indicating that Fzd4-mediated Lin28b expression in CAFs promotes PDAC growth." (PMID 37898598, 2023). "In mouse models of TNBC, tumor-derived EVs containing the pluripotent factor Lin28B were found to upregulate the expression of CXCLs (CXCL1, CXCL2, CXCL3, and CXCL5) in the lung tissue, resulting in neutrophil infiltration." (PMID 37496019, 2023). "The gene expression analysis revealed that the “tumour-specific” TE-derived transcript of LIN28B is expressed in the placenta (in both first and third trimester placental tissues)." (PMID 37269361, 2023). "A study has indicated that in OSCC, the LIN28B-Let7 axis enhances tumor cell stemness and promotes tumorigenesis by mediating SOX2 expression through HMGA2." (PMID 37237385, 2023).
tumor (continued). "Let-7s are a regulatory target of Lin28B and display an extensive inhibitory role in tumor progression, we, therefore, set out to focus on let-7s’ role in pre-metastatic niche modification." (PMID 35173168, 2022). "With the fresh tumor specimens, we obtained similar results suggesting that Lin28B was upregulated in 11 out of 24 tumor tissues." (PMID 35173168, 2022). "We concluded that tumor-derived exosomes recapitulate the Lin28B-induced immune-suppressive pre-metastatic niche, which can be counteracted by PD-L2 and IL-6 elimination." (PMID 35173168, 2022). "We previously demonstrated that LIN28B promotes tumor growth and inhibits apoptosis by modulating the AKT2/FOXO3A/BIM axis." (PMID 35780125, 2022). "Lin28a overexpression occurs with equal frequency in large fractions of tumors and inhibition of Lin28a and Lin28b via siRNA inhibits tumor growth." (PMID 35453602, 2022). "Recent improvements provide a novel insight in relationship between LIN28B and various tumor types, including colon cancer, ovarian cancer, liver cancer, neuroblastoma." (PMID 35633416, 2022). "Altogether, our study elucidated a mechanism that Lin28B promotes metastasis by influencing tumor exosomal let-7s content." (PMID 35173168, 2022). "We determine that Lin28B can establish an immunosuppressive pre-metastatic niche by inducing neutrophil infiltration and N2 conversion, which depends on the tumor-released exosomes with low let-7s." (PMID 35173168, 2022). "The TRIM71 protein, which regulates early development and differentiation, can act as a tumor suppressor by post-transcriptionally repressing LIN28B and modulating the let-7/Hmga2 axis." (PMID 34439740, 2021). "Low Lin28B expression correlated with the less aggressive OC, lower tumour malignancy and better chemotherapy response, whereas high IGF-II expression correlated with very low survival and sensitivity to paclitaxel, yet let-7a itself did not affect survival." (PMID 34267805, 2021). "Further, LINC00467 inhibited the expression of a tumor suppressive miRNA: miR-138-5p, and up-regulated the protein level of an oncogene: LIN28B, via a direct interaction of each other." (PMID 33996559, 2021). "LIN28B is highly expressed in circulating tumor cells of PDAC patients and is a driver of metastatic dissemination." (PMID 34591242, 2021). "Downstream of AVIL, FOXM1 is implicated in angiogenesis, tumor invasion, and EMT, while LIN28B allows expression of oncogenes by inhibiting let-7 miRNAs." (PMID 34948433, 2021). "The Transwell 2D invasion assays revealed CDX2 knockdown enhanced tumor cell invasion in the context of LIN28B overexpression." (PMID 33755595, 2021). "In more than 15% of tissue malignancies, either Lin28A or Lin28B is reactivated while let-7 is repressed, resulting in the elevated expression of let-7 target genes as well as alterations in tumor cell metabolism." (PMID 34572067, 2021). "let-7a is a tumor suppressor miRNA whose expression is regulated by several signaling molecules, and the NF-κB/Lin28B signaling pathway is one of the most important pathways involved." (PMID 35069510, 2021). "DFMO treatment induced LIN28B downregulation, inhibiting NB tumor progression by decreasing the glycolytic metabolic rate of NB tumor cells." (PMID 34072462, 2021). "More recently, nuclear DR5 was discovered to result in increased levels of malignancy-promoting factors HMGA2 and Lin28B and enhanced tumor cell proliferation in vitro and in vivo." (PMID 32784606, 2020). "Although this condition accelerates cell growth in vitro, when re-expressed, miR-125a-5p functions as a tumor suppressor by directly targeting lin-28 homolog B (LIN28B), which serves as its functional effector." (PMID 33348804, 2020). "The LIN28B is upregulated to repress the function of the tumor suppressor miRNA let-7 family in the diverse tumor types and serve as a regulator of miRNA 20,39-41." (PMID 32284747, 2020).
tumor (continued). "LIN28B functions by blocking the maturity of tumor-suppressing microRNA (miRNA) let-7 family, which subsequently causes overexpression of numerous oncogenes, such as C-MYC and K-RAS, thereby supporting tumorigenesis and tumor growth 18,19." (PMID 32284747, 2020). "Since Lin28b upregulation is critically involved in the development of different tumour types it likely contributes to tumour development and/or maintenance in tumours in which LIP levels are increased." (PMID 31240246, 2019). "On the other hand, forced expression of LIN28B promoted malignant transformation of parental hBMSC cells as shown by enhanced in vitro colony formation, doxorubicin resistance, and in vivo tumor formation in immunocompromised mice." (PMID 31147574, 2019). "We conducted rescue experiments to determine the importance of Lin28b in miR-498-regulated tumor suppression in GC." (PMID 29970131, 2018). "It was well demonstrated that LIN28B selectively represses certain miRNAs, including let-7,10,11,50 one of the first-identified tumor suppressor miRNAs,28 which controls the expression of hundreds of target genes." (PMID 30174831, 2018). "We conducted rescue experiments to determine the importance of Lin28b in UFC1-regulated tumor progression in GC." (PMID 29970131, 2018). "Lin28B is involved in cell growth and reprogramming and suppresses the biogenesis of the let-7 microRNAs (miRNAs) that function as tumor suppressors by silencing the expression of several oncogenes such as MYC and RAS." (PMID 29587439, 2018). "LIN28B shRNA dramatically decreased the tumor size, while LIN28B overexpression increased the tumor size." (PMID 30174831, 2018). "Lin28b acts as an oncogene and facilitates tumor progression though let-7-dependent and -independent mechanisms." (PMID 29970131, 2018). "LIN28A and LIN28B exert their biological functions through repressing the biogenesis of the tumor suppressor let-7 microRNA family as well as modifying the translation efficiency of mRNAs that it binds." (PMID 28400788, 2017). "We and others reported previously that overexpression of LIN28B contributes to tumor aggressiveness and metastasis through let-7-dependent mechanisms." (PMID 28693523, 2017). "They further demonstrated that LIN28 knockdown suppressed tumor cell proliferation, whereas LIN28B overexpression promoted tumor cell growth, clonal proliferation, and invasiveness." (PMID 28910332, 2017). "The most well-characterized function of Lin28B is to repress the biogenesis of a family of 12 tumor suppressor miRNAs, collectively referred to as let-7." (PMID 28947981, 2017). "Lin28B has recently been suggested to act as an oncogene, facilitating malignant transformation and tumor progression." (PMID 28947981, 2017). "LIN28B expression is reportedly induced by the c-Myc oncogenic transcription factor in multiple human and mouse tumor models." (PMID 28084458, 2017). "Results from another study showed that LIN28B promotes oncogenesis and tumor progression in head and neck cancer cells by repressing let-7 miRNAs." (PMID 28400788, 2017). "Upregulation of Lin28B has also been observed in various tumor types, particularly at the initial stage of the disease." (PMID 27821801, 2016). "Since TRIM71 inhibits tumor growth initiated by Lin28B, we examined the function of TRIM71 in suppressing tumorigenic phenotypes." (PMID 27821801, 2016). "To establish a functional role of TRIM71 in Lin28B-mediated cellular transformation and tumor formation, we directly injected NIH/3T3 cells used in soft agar colony-formation assay into nude mice and compared their abilities to form tumors." (PMID 27821801, 2016).
tumor (continued). "The expression levels of anti-Let-7 target genes (in humans: HMGA2, IGF2BP2, and LIN28B; in mice: Igf2bp2, Nras, and Tgfbr1) were examined in each tumor mass and brain tissue from mice." (PMID 27102443, 2016). "TRIM71 overexpression opposed Lin28B-induced transformation in primary cells and inhibited tumor formation in a mouse model." (PMID 27821801, 2016). "TRIM71 suppressed cellular transformation and tumor formation by directly inhibiting the activity of the oncoprotein, Lin28B." (PMID 27821801, 2016). "In contrast to the mH2A1 expression pattern, the highest expression of Lin28B was observed in grade 3 tumor tissues, while the lowest expression of Lin28B was observed in normal tissues." (PMID 26028027, 2016). "Evaluating with Oncomine data, we found most target genes (BCL2, ERBB2/3, SIRT7, ETS1, Mcl-1, IL6R, and LIN28B) were significantly activated in HCC tumor tissues, consistent with miR-125b underexpression." (PMID 25861255, 2015). "Overexpression of LIN28B was identified in a major fraction of OSCC samples(39/58) and significantly associated with tumor size (P = 0.049) and advanced clinical stages (P = 0.0286)." (PMID 26478718, 2015). "In this cellular compartment, TRAIL-R2, acting as a negative regulator of let-7 miRNA maturation, increases the expression of the respective targets high mobility group AT-hook 2 (HMGA2) and lin-28 homolog B (Lin28B), and enhances tumor cell proliferation." (PMID 25909161, 2015). "We found frequent overexpression of the cell-reprogramming factors LIN28A and LIN28B in AT/RT primary tumor samples and cell lines." (PMID 25638158, 2015). "MiR-26a, which is downregulated in PCa, was shown to inhibit growth and metastatic progression of human-tumor xenografts, probably by targeting lin-28 homolog B (Lin28B) and zinc finger CCHC domain containing 11 (ZCCHC11)." (PMID 25250334, 2014). "The let-7 tumour suppressor microRNA family members are known to regulate chemosensitivity, while LIN28B promotes malignancy mainly by inhibiting let-7 biogenesis." (PMID 25360631, 2014). "C-/N-Myc induce LIN28B expression in multiple human and mouse tumour models, resulting in let-7 repression and cell proliferation." (PMID 25360631, 2014). "As anticipated, LIN28B overexpression correlated with reduced patient survival and an increased likelihood of tumour recurrence." (PMID 25360631, 2014). "The ability of LIN28B to regulate let-7, a bona fide tumour-suppressor, is consistent with its developmental role in regulating cell proliferation and differentiation." (PMID 25360631, 2014). "LIN28B is a developmentally regulated RNA-binding protein that promotes tumourigenesis by blocking the post-transcriptional processing of the tumour-suppressive pri-/pre-let-7 microRNA." (PMID 25360631, 2014). "Consistent with previous reports, LIN28B was significantly overexpressed in tumour tissues compared to normal tissues (p<0.001)." (PMID 25360631, 2014). "The primary known targets of LIN28A and the related protein LIN28B are the let-7 family of tumor suppressing microRNAs." (PMID 23846349, 2013). "The calculated frequencies of Lin28B gene in the libraries of immature, mature, and tumor groups were 22, 5 and 28, respectively, with ratio between tumor and mature groups (tumor/mature) estimated at 5.6." (PMID 24244607, 2013). "Univariate analysis revealed that tumor grade (P=0.047), vascular invasion (P=0.038), AJCC stage (P<0.001), BCLC stage (P=0.030) and circulating Lin28B (P=0.001) were significantly associated with decreased RFS." (PMID 24244607, 2013). "In conclusion, we have demonstrated a novel mechanism by which Lin28b over-expression promotes tumour progression via additional Let-7 gene targets such as CCND2, IGF2BP2, and IGF1R." (PMID 23482325, 2012). "Our results are consistent with Liang’s study, which indicated that miR-125b exerts tumor-suppressive effects in hepatic carcinogenesis through the suppression of oncogene LIN28B expression." (PMID 22942733, 2012).
tumor (continued). "While Lin28b has been reported to promote tumour progression, the precise mechanism(s) thereof has remained unclear." (PMID 23482325, 2012). "Heterogeneous expression of HMGA2 and lin28B was observed in let-7a-treated tumors suggesting non uniform distribution of synthetic miRNA within the tumor." (PMID 21853155, 2011). "In addition, LIN28B gene expression was highly upregulated in tissues from MB patients compared to non-tumour brain tissues, where its higher expression was correlated with a higher metastasis rate and a lower patient survival rate." (PMID 40265419, 2025). "Additionally, IHC analysis of eight paired tumor and adjacent normal tissues revealed markedly elevated LIN28B expression in tumor tissues." (PMID 40740861, 2025). "The RNA-binding protein LIN28B represses the biogenesis of the tumor suppressor let-7." (PMID 38976670, 2024). "Consequently, LIN28B has been characterized as a lncRNA LINC01605-interacting protein, illuminating a multifaceted mechanism underlying LINC01605-driven PDAC tumor progression and liver metastasis." (PMID 39048994, 2024). "Given that LIN28B acts by negatively regulating the biogenesis of the tumor suppressor let-7 miRNAs, we reasoned that selective interference with the LIN28B/let-7 miRNA interaction would increase let-7 miRNA levels, ultimately leading to reduced NB aggressiveness." (PMID 38732012, 2024). "Moreover, our results show for the first time that the tumour-specific, TE transcript of LIN28B is a placental transcript that becomes reactivated in tumours." (PMID 37269361, 2023). "What’s more, Wnt5a secreted by tumor epithelium could also upregulate Lin28b in surrounding CAFs even in response to low glucose concentration." (PMID 37898598, 2023). "Next, we implanted 14837T, 14838T, or 15376T into the pancreas of mice and found that orthotopic model of 15376T expressed high levels of Lin28b in both tumor and stroma, while 14837T and 14838T tumors demonstrated only background levels of staining for Lin28b." (PMID 37898598, 2023). "Lin28B increased IL-6 and IL-10 production, which could convert infiltrated neutrophils from tumor-suppressive to tumor-promoting." (PMID 37496019, 2023). "All together, these data indicated that tumor cells with high levels of Lin28b (Lin28bhigh) could upregulate stroma Lin28b expression." (PMID 37898598, 2023). "We found that 23 of 80 PDAC samples (28.75%) expressed high levels of LIN28B in tumor epithelium." (PMID 37898598, 2023). "However, in our study, we found LIN28B overexpression increased tumor sphere formation in a Group 3 MB cell line." (PMID 37341142, 2023). "Here, we investigate the role of the LIN28B pathway in G3 MB and demonstrate that the LIN28B–lethal‐7 (let‐7; a microRNA that is a tumor suppressor)–lymphokine‐activated killer T‐cell‐originated protein kinase (PBK; also known as PDZ‐binding kinase) axis promotes G3 MB proliferation." (PMID 37341142, 2023). "To test this hypothesis, we genetically altered LIN28B expression in Group 3 MB cells and compared tumor cell viability and growth in vitro and in vivo and we determined the impact on downstream regulation of let‐7 and PBK." (PMID 37341142, 2023). "In addition, since our data indicated that Wnt5a-Fzd4 pathway is essential for activation of Lin28b, we also tested the role of Fzd4 in tumor growth." (PMID 37898598, 2023). "However, Lin28B expression markedly initiated the metastatic lung burden and reduced the overall survival of tumor-bearing mice." (PMID 35173168, 2022). "Thus, our results reveal a direct functional link between Lin28B and immunosuppression, suggesting a metastasis-related mechanism in the early stage of tumor growth." (PMID 35173168, 2022). "Thus, our results indicate Lin28B expression in the primary tumor can alter the “immune state in the metastatic niche”." (PMID 35173168, 2022).